MTRES1 (mitochondrial transcription rescue factor 1)
Description:
Mitochondrial RNA-binding protein involved in mitochondrial transcription regulation. Functions as a protective factor to maintain proper mitochondrial RNA level during stress. Acts at the transcription level and its protective function depends on its RNA binding ability. Part of a mitoribosome-associated quality control pathway that prevents aberrant translation by responding to interruptions during elongation. As heterodimer with MTRF, ejects the unfinished nascent chain and peptidyl transfer RNA (tRNA), respectively, from stalled ribosomes. Recruitment of mitoribosome biogenesis factors to these quality control intermediates suggests additional roles for MTRES1 and MTRF during mitoribosome rescue.
Synonyms: C6orf203; HSPC230; PRED31
Tractability: Small molecule: a structure with a bound ligand is known.
Gene: Protein-coding gene on chromosome 6 (107,028,184 to 107,051,586, forward strand). Ensembl gene ENSG00000130349.
Subcellular location: Mitochondrion matrix
Pathways (Reactome):
Metabolism of proteins: Mitochondrial ribosome-associated quality control
Gene Ontology:
Molecular function: protein binding; ribosomal large subunit binding; RNA binding; tRNA binding
Biological process: regulation of mitochondrial transcription
Cellular component: mitochondrial matrix; mitochondrion
Genetic constraint (gnomAD): Loss-of-function variants: 15 observed, 20.71 expected, observed/expected ratio (o/e) 0.72, 90% interval 0.48 to 1.12. The upper end of that interval is the gene's LOEUF score, 1.12, which puts it in group 4 of 6, group 1 being the genes least tolerant of losing a copy. Missense variants: 266 observed, 287.96 expected, observed/expected ratio (o/e) 0.92, 90% interval 0.83 to 1.02. Synonymous variants: 94 observed, 104.55 expected, observed/expected ratio (o/e) 0.9, 90% interval 0.76 to 1.07.
Homologues: Orthologues: chimpanzee MTRES1 (99% identical), macaque MTRES1 (95% identical), dog MTRES1 (82% identical), rabbit MTRES1 (81% identical), pig MTRES1 (81% identical), mouse Mtres1 (79% identical), rat Mtres1 (78% identical), guinea pig MTRES1 (73% identical), tropical clawed frog mtres1 (46% identical), zebrafish mtres1 (38% identical), Drosophila melanogaster CG4884 (25% identical), Caenorhabditis elegans C47B2.9 (13% identical).
Diseases named in the same sentence as MTRES1 in open-access papers:
MTRES1 is named in the same sentence as 3 diseases in open-access papers, as found by Europe PMC text mining. Sharing a sentence is not in itself a finding about the gene and the disease.
MTRES1 shares sentences with these, for which no sentence is quoted: breast carcinoma (1 paper); osteosarcoma (1); respiratory failure (1).